KIT (KIT proto-oncogene, receptor tyrosine kinase)
Diseases named in the same sentence as KIT in open-access papers (continued):
Sharing a sentence is not in itself a finding about the gene and the disease.
meningioma (continued). "Despite reported absence of KIT expression in meningiomas, our initial observation of its mRNA expression (by RT-PCR) in some cases evoked our interest to ascertain its status in the present study." (PMID 22672386, 2012). "The third study focused on the analysis of KIT immunoexpression in 37 meningiomas and reported lack of its expression." (PMID 22672386, 2012). "Contrary to earlier reports of absence of KIT expression in meningiomas, the present study showed its expression in 20.6% cases." (PMID 22672386, 2012). "In all the earlier studies, KIT expression was reported to be absent in meningiomas." (PMID 22672386, 2012). "A meningioma WHO I used as control lacked KIT expression but showed some Zonulin expression." (PMID 22672386, 2012). "Further, by co-staining Zonulin with a marker for blood vessels (GSI), it was demonstrated that the blood brain barrier was degraded in meningioma WHO III unlike meningioma WHO I. The current finding on the single meningioma grade III being KIT negative reflects a chance occurrence." (PMID 22672386, 2012). "Interestingly, of the 7 KIT positive meningiomas, none showed copy number gain of this gene." (PMID 22672386, 2012). "In a recent high-throughput kinome screen in NF2-null human arachnoidal and meningioma cells, we showed activation of EPH RTKs, c-KIT, and SFK members independent of mTORC1/2 activation." (PMID 32144278, 2020). "KIT and/or KITLG expression quantification in meningiomas was not performed thus far." (PMID 22672386, 2012).
Merkel cell carcinoma (6 papers, 2014 to 2025). "In a case series of feline (and canine) Merkel cell carcinomas, all three feline specimens reacted positive for KIT, but the lymphoid origin could not be demonstrated." (PMID 37835664, 2023).
neutropenia (6 papers, 2019 to 2025). A decrease in the number of neutrophils found in the blood. "Consistent with this expression profile, targeting KIT with a mAb or small molecule has been associated with neutropenia, graying of hair, changes in taste perception, and defects in spermatogenesis." (PMID 36369358, 2022). "Both FLT3 and KIT kinases play an important role in hematopoiesis and their inhibition may result in neutropenia as observed in the clinical trials for barasertib." (PMID 33915740, 2021).
Obesity (6 papers, 2012 to 2024). Accumulation of substantial excess body fat. "Together our data would suggest that as both obesity and idiopathic gastroparesis result in increased KIT mRNA expression yet these two conditions have opposing effects on gastric emptying, changes in KIT mRNA expression do not correlate with changes in gastric emptying." (PMID 31221130, 2019). "In the independent validation, cohort 1 of n = 32 patients with obesity whose VAT gene expression was assessed by microarrays, all MC genes probe sets (KIT, TPSB2, CMA1) exhibited significant negative correlations with macrophage gene probes (CD68, Mac2, IGTAX(CD11c))." (PMID 32575785, 2020).
pulmonary hypertension (6 papers, 2012 to 2024). Increased pressure within the pulmonary circulation due to lung or heart disorder. "Also, the selective VEGFR blocker cabozatinib tended to exacerbate pulmonary hypertension (RV hypertrophy), unlike non-selective VEFGR blockers that additionally target PDGFR-β or FGFR 1 (regorafenib), PDGFR-β or c-KIT (sunitinib), or b-RAF, c-KIT, or PDGFR-β (sorafenib)." (PMID 39684570, 2024).
thymic epithelial tumors (6 papers, 2021 to 2023). "The expression of KIT is reportedly associated with survival in thymic epithelial tumors, and KIT targeting regimens have been developed." (PMID 34680386, 2021). "It has been pointed out that thymic epithelial tumors depend on tumor angiogenesis and growth signals from c‐KIT and EGFR for propagation." (PMID 37474689, 2023). "This article reports on comprehensive genomic profiling of thymic epithelial tumors in the setting of advanced disease, identifying clinically-relevant genomic alterations in the KIT, PI3K, CDKN2A/B, or NTRK genes, which suggests potential precision medicine approaches using targeted agents." (PMID 35749302, 2022).
anal melanoma (5 papers, 2008 to 2015). A melanoma arising from the anus. "A 62-year-old woman with anal melanoma and widespread pulmonary metastases complicated by impending respiratory failure, had a D820Y mutation in exon 17 of KIT in her primary tumour." (PMID 20372153, 2010). "This is supported by two case reports published very recently of single patients suffering from metastasising anal melanoma that harboured a KIT mutation in exon 11 and exon 13, respectively." (PMID 19018266, 2008). "A patient with KIT V560D mutant anal melanoma with isolated lung metastases had a complete response to a combination of Nexavar and Temozolomide." (PMID 21479172, 2011).
B-cell lymphomas (5 papers, 2010 to 2024). "Similarities were also noted between CLBL-1 and other targeted B-cell lymphoma gene expression studies, including KIT (almost 400-fold based on qRT-PCR) and ZAP70 downregulation (decreased 10 fold)." (PMID 27639374, 2016). "Vice versa, neoplastic cells in T cell- or B cell-lymphomas did not express MC-related antigens (KIT, tryptase, chymase) in any of the animals examined." (PMID 21297223, 2010). "In fact, neoplastic MC did not express any of the T cell- or B cell-restricted antigens analyzed (except ALK), and the T cell- and B cell-lymphomas did not express MC antigens such as KIT, tryptase, or chymase." (PMID 21297223, 2010).
colorectal adenocarcinoma (5 papers, 2014 to 2022). The most common type of colorectal carcinoma. "There are 59 invasive colorectal adenocarcinoma cases available in the database; among them, 1 case (TCGA-AA-3680) shows homozygous deletion of miR-34c and 3 cases (TCGA-AA-3561, TCGA-AG-3586 and TCGA-AG-3892) exhibit KIT mRNA up-regulation but none cases show decreased miR-34a or KITLG alteration." (PMID 25213795, 2014). "The protein expressions of Trex-1, c-KIT, and Flt3, but not PKCα/β/γ and VEGFR1, were down-regulated in midostaurin-treated colorectal adenocarcinoma cells and macrophages." (PMID 36230769, 2022).
conjunctival melanoma (5 papers, 2018 to 2025). "As with UM, the off-label use of imatinib should be considered with care in patients with KIT-mutated conjunctival melanoma, as little is known about the chance of success." (PMID 32718045, 2020). "For example, a study of 53 patients showed a higher percentage of KIT than B-Raf mutations in Chinese patients with conjunctival melanoma." (PMID 30909967, 2019). "NRAS is mutated in ~20% of conjunctival melanomas, and KIT mutations are reported in 0–7%." (PMID 32718045, 2020). "In patients with conjunctival melanoma, which involves dysregulation of the MAPK and PI3K/AKT/mTOR pathways, mutations in BRAF, NRAS, and NF1 are commonly observed, while KIT and PTEN mutations occur less frequently." (PMID 41001300, 2025).
endometrial stromal sarcoma (5 papers, 2010 to 2024). "Given the presence of a mass attached to the uterus and the diffuse positivity for cyclin D1 and KIT, a diagnosis of high-grade endometrial stromal sarcoma was initially favored." (PMID 39777304, 2024). "Secondly, this patient with rare YWHAE-FAM22 translocated endometrial stromal sarcoma showed a remarkable response to VEGFR/KIT inhibitor pazopanib." (PMID 29357824, 2018). "Recently, it was reported that this specific subtype of endometrial stromal sarcoma overexpresses CD117, but has no KIT mutations." (PMID 29357824, 2018).
fibrosis (5 papers, 2014 to 2021). the formation of excess fibrous connective tissue in an organ or tissue in a reparative or reactive process. "Additionally, in fibrotic tissues of human myectomies increased c-KIT levels correlated with higher markers of cardiac fibrosis in the HCM group compared to controls suggesting a possible link to a cardiac fibrosis already known to be associated with HCM." (PMID 33469076, 2021). "Perhaps more significantly, the recognition of imatinib activity against other kinases, notably KIT and PDGFR (platelet-derived growth factor receptor), has led to its effective use in other oncology indications and ongoing clinical trials in fibrosis." (PMID 24768818, 2014).
gastroparesis (5 papers, 2014 to 2023). Paralysis of the muscles of the stomach wall resulting in delayed emptying of the gastric contents into the small intestine. "MiR-10b-5p regulates development and function of ICCs and pancreatic β cells through the KLF11-KIT pathway, in murine models, knockout of mir-10b in KIT+ cells led to DM and gastroparesis." (PMID 33806716, 2021). "Moreover, there was a significant increase in KIT mRNA expression in the idiopathic gastroparesis subjects compared to the low BMI control subjects." (PMID 31221130, 2019). "However, not consistent with this interpretation is our previous and current study in which we did not detect any significant differences in expression of KIT, ANO1 or KITLG between the high BMI control subjects and the low BMI idiopathic gastroparesis subjects." (PMID 31221130, 2019).
hemangioma (5 papers, 2012 to 2025). A benign vascular lesion characterized by the formation of capillary-sized or cavernous vascular channels. "Although several publications have examined the c-KIT in hemangiomas from the body in general, to the best of our knowledge, there are no publications regarding the presence of the c-KIT in Cavernous Venous Hemangiomas or in other types of vascular tumors specifically involving the orbit." (PMID 34439864, 2021). "Most studies examining c-KIT in angiomas were not specific to cavernous venous hemangiomas and were not from any specific part of the body." (PMID 34439864, 2021).
Immunodeficiency (5 papers, 2021 to 2024). Failure of the immune system to protect the body adequately from infection, due to the absence or insufficiency of some component process or substance. "Furthermore, the keywords related to basic research (growth-factor receptor, immunohistochemistry, and KIT) and immune disease (systemic-lupus-erythematosus, lichen-planus, t-cells, and red-cell aplasia) have increased in recent years." (PMID 37029418, 2023).
neuroendocrine carcinoma (5 papers, 2016 to 2025). A malignant neuroendocrine neoplasm composed of cells containing secretory granules that stain positive for NSE and chromogranin.
neurofibromatosis (5 papers, 2010 to 2025). A hereditary neoplastic syndrome in which tumors grow in the nervous system. "Multiple sporadic GISTs have been described in patients who do not have germline mutations in KIT/PDGFRA or neurofibromatosis." (PMID 20946677, 2010). "Conversely, for KIT/PDGFRA WT cases with clinical features of a genetic disease, the multigene second-level panel could help to characterize the NF1-related GIST and to make a diagnosis of neurofibromatosis genetic disease." (PMID 41407759, 2025).
osteoporosis (5 papers, 2016 to 2026). A condition of reduced bone mass, with decreased cortical thickness and a decrease in the number and size of the trabeculae of cancellous bone (but normal chemical composition), resulting in increased fracture incidence. "We further discuss the transformative impact of KIT-directed tyrosine kinase inhibitors, particularly avapritinib, which has demonstrated for the first time the ability to reverse not only osteoporosis but also osteosclerosis." (PMID 41677670, 2026).
ovarian dysgerminomas (5 papers, 2007 to 2023). "Taken together, c-KIT mutations occur in approximately half of pure ovarian dysgerminoma cases, all residing in exon 17, indicating a role in the etiology of the disease." (PMID 22937135, 2012). "Mutations in c-KIT codon 816 were found in 5 (33%) and mutations in codon 822 in 3 (20%) out of the 15 pure ovarian dysgerminoma cases (case 17, 19, 22, 25, 31 and 21, 24, 27 respectively), accounting for 53% of cases analyzed." (PMID 22937135, 2012). "c-KIT codon 816 mutations were detected in five out of the total of 31 cases (all found in pure ovarian dysgerminomas)." (PMID 22937135, 2012). "Furthermore, KIT amplification or somatic activation (due to mutations in exon 17, codon 816) is present in 27–53% of ovarian dysgerminomas." (PMID 37575996, 2023). "Unexpectedly, this KIT D816A variant was also detected in the prior ovarian dysgerminoma sample." (PMID 33246418, 2020). "The results presented here suggest that in about half of ovarian dysgerminomas activating mutations in c-KIT play a role, with about a third consisting of codon 816 mutations, as has been reported by others, while the remaining 20% consisted of N822K mutations." (PMID 22937135, 2012). "Here we analyzed fifteen cases of pure ovarian dysgerminomas and found that c-KIT is expressed, although variable, in all but two of the cases analyzed." (PMID 22937135, 2012). "In brief, the KIT D816A variation initially induces the development of ovarian dysgerminoma." (PMID 33246418, 2020). "In total activating c-KIT mutations were found in 53% of ovarian dysgerminomas without DSD." (PMID 22937135, 2012). "Although most ovarian dysgerminomas express c-KIT, we could not find a correlation between expression and c-KIT exon 17 mutations." (PMID 22937135, 2012). "Staining for c-KIT was variable in the whole series analyzed, ranging from absent through intermediate to strong staining and no clear difference between the DSD and ovarian dysgerminoma subgroups could be seen." (PMID 22937135, 2012).
renal carcinoma (5 papers, 2014 to 2024). A carcinoma arising from the epithelium of the renal parenchyma or the renal pelvis. "In the present study, apart from SKCM, kidney renal papillary cell carcinoma exhibited CDK2, CDK4, KIT, and VWF Cox coefficient values of > 0, indicating that the high expression of these four key genes is a risk factor for patients with renal carcinoma." (PMID 34582363, 2021).
renal oncocytoma (5 papers, 2014 to 2025). "Rare oncocytic renal tumors resemble oncocytoma, yet show diffuse keratin 7 (KRT7) staining and negative KIT staining, which would be unexpected for renal oncocytoma (RO)." (PMID 39980061, 2025). "While the histological features of LOT of the kidney are similar to those of renal oncocytoma, LOT immunohistochemically expresses keratin 7 (KRT7) but not KIT while renal oncocytoma expresses KIT." (PMID 39980061, 2025).
skin tumors (5 papers, 2021 to 2025). "MCTs, accounting for approximately 21% of canine skin tumors, are often driven by mutations in the KIT proto-oncogene, leading to an uncontrolled proliferation of mast cells." (PMID 41394861, 2025). "Although commercial laboratory tests showed the same mutation of exon 8, we could not compare the sequence similarity of other c-KIT mutations between spleen and skin tumors, even among several skin tumors, because tissue samples for RNA extraction were unavailable." (PMID 36138037, 2022).
small cell carcinoma (5 papers, 2007 to 2023). A neuroendocrine carcinoma composed of small malignant cells which are often said to resemble "oat cells" under the microscope. "No KIT mutations or presence of Y-chromosome material was detected in any of the small cell carcinomas or immature teratomas." (PMID 17274819, 2007).
superficial spreading melanoma (5 papers, 2017 to 2025). A type of melanoma that typically occurs in light-skinned individuals ranging in age from young adults to the elderly. "In turn, BRAF mutations are the dominating genetic causative factor in superficial spreading melanoma (SSM), whereas for ALM, typical mutations can be found in the BRAF, NRAS, KIT, and NF1 genes." (PMID 34575876, 2021).
type 2 diabetes (5 papers, 2018 to 2024). "We found that miR-10a/b-5p induces the growth of ICC and pancreatic β cells by targeting KLF11 (a causative gene for maturity-onset of diabetes of the young), which negatively regulates expression of KIT and insulin (INS) genes." (PMID 38396943, 2024). "In this report, the authors demonstrated that overexpression of c-KIT in beta cells ameliorates glucose metabolism by increasing insulin secretion and thus implying that this receptor could have a protective role in preventing type 2 diabetes." (PMID 29795582, 2018).
urothelial carcinoma (5 papers, 2023 to 2025). A malignant neoplasm derived from the transitional epithelium of the urinary tract (urinary bladder, ureter, urethra, or renal pelvis). "Recognizing some morphological features and subtypes of urothelial carcinoma could be a useful prognostic factor in treatment planning; thus, schistosomal/urothelial bladder cancer should be considered a histological variant being positively correlated with T staging and CD117/KIT overexpression." (PMID 37338655, 2023). "In urothelial carcinoma (UC) cells, ZNF671 re-expression inhibited tumor growth and invasion, in conjunction with downregulation of cancer stem cell markers (c-KIT, NANOG, OCT4)." (PMID 39595048, 2024). "The identification of c-KIT and AVPR1A as two differentially expressed genes with known effects on promotion of cell growth and mTORC1 activation in uroepithelial carcinomas and other malignancies is likely a first step toward the exciting discovery of new therapies for this devastating disease." (PMID 38028758, 2023).
viral infection (5 papers, 2012 to 2022). "This multi-kinase drug also inhibits Src family kinases (SFK), BCR-ABL, platelet-derived growth factor receptor (PDGFR) and c-KIT and has previously been shown to inhibit cancer progression as well as viral infection." (PMID 36297233, 2022).
adenoma (4 papers, 2013 to 2024). A neoplasm arising from the epithelium. "The results of the sequencing analysis in the patient with the large HGD adenoma, indicated that APC (Adenomatous Polyposis Coli), KIT, and possibly JAK3 were the most likely early drivers of tumorigenesis in these patients." (PMID 39507544, 2024).
Alzheimer disease (4 papers, 2016 to 2024). A progressive, neurodegenerative disease characterized by loss of function and death of nerve cells in several areas of the brain leading to loss of cognitive function such as memory and language. "Recently, it has also been shown that KIT improves cognitive dysfunction in patients with Alzheimer's disease." (PMID 34765515, 2021).
chronic myelomonocytic leukemia (4 papers, 2013 to 2025). A myelodysplastic/myeloproliferative neoplasm which is characterized by persistent monocytosis, absence of a Philadelphia chromosome and BCR/ABL fusion gene, fewer than 20 percent blasts in the bone marrow and blood, myelodysplasia, and absence of PDGFRA or PDGFRB rearrangement. "The patient achieved sustained complete remission(CR)of SM, with persistent molecular negativity for the KIT D816V mutation, but ultimately succumbed to disease progression to chronic myelomonocytic leukemia(CMML)." (PMID 40623907, 2025). "Another similar case of an ovarian germ cell tumor carrying a KIT D816H mutation was also recently reported in which the chemotherapy was complicated by the development of SM with chronic myelomonocytic leukemia harboring this same mutation." (PMID 33246418, 2020).